RAG1 (recombination activating 1)
Diseases named in the same sentence as RAG1 in open-access papers (continued):
Sharing a sentence is not in itself a finding about the gene and the disease.
fibrodysplasia ossificans progressiva (1 paper, 2022). Fibrodysplasia ossificans progressiva (FOP) is a severely disabling heritable disorder of connective tissue characterized by congenital malformations of the great toes and progressive heterotopic ossification that forms qualitatively normal bone in characteristic extraskeletal sites. "Lymphocytes are present at early stages of fibrodysplasia ossificans progressiva (FOP), a fully penetrant and lethal genetic form of HO,23,24 while mice lacking functional T and B lymphocytes (Rag1-/- mutant mice) have been shown to develop less HO after non-neurological trauma." (PMID 35317305, 2022).
hemophilia A (1 paper, 2022). The most common form of hemophilia characterized by spontaneous or prolonged hemorrhages due to factor VIII deficiency. "In order to evaluate FVIII output and stability in adult mice, without confounding factors due to anti-FVIII immune responses, that are more likely to develop upon treatment at this age, we generated immune-deficient hemophilia A mice, by crossing F8 KO with Rag1 KO mice (RagHemoA)." (PMID 35508619, 2022).
Hodgkins lymphoma (1 paper, 2020). A heterogeneous group of malignant lymphoid neoplasms of B-cell origin characterized histologically by the presence of Hodgkin and Reed-Sternberg (HRS) cells in the vast majority of cases. "Hodgkin lymphoma and intra-cranial B cell lymphoma were noted in children with RAG1 and CORO1A defects, respectively." (PMID 33628209, 2020).
Hydrocephalus (1 paper, 2017). Hydrocephalus is an active distension of the ventricular system of the brain resulting from inadequate passage of CSF from its point of production within the cerebral ventricles to its point of absorption into the systemic circulation. "Unexpectedly, we observed that the majority of the mice carrying both the floxed KRasG12V gene and the Rag1-Cre developed an abnormal gait and light sensitivity within two months and post-mortem examination revealed hydrocephalus and CNS vascular proliferations with features of haemangioblastoma." (PMID 28322325, 2017).
Hyperkeratosis (1 paper, 2020). Hyperkeratosis is a histopathological term defining a thickened stratum corneum and may be present in many different skin conditions, with many possible overlaps. "Tamoxifen induced a skin phenotype very similar to Card14LSL-E138A/+Rosa26CreERT2/+Rag1+/+ controls, with acanthosis, hyperkeratosis, S100A9+ myeloid cell infiltration and expression of chemokines and proinflammatory cytokines at 5d following tamoxifen injection." (PMID 32597759, 2020).
hypophysis (1 paper, 2021). "The separate analysis of gh and rag1 expression levels readily reveals whether interactions between genes or inhibitors affect only T cells, or both T cells and growth hormone-producing cells in the hypophysis, the latter situation being indicative of potential off-target effects." (PMID 34671088, 2021).
infarcts (1 paper, 2020). "Strikingly, the removal of platelets from the circulation of Rag1−/− mice that received adoptive transfer of Treg cells has led to infarcts that were as small as in naive Rag1−/− mice after tMCAO." (PMID 33123127, 2020).
infectious colitis (1 paper, 2021). A viral or bacterial infectious process affecting the large intestine. "Since DCLK1 was significantly overexpressed in Rag-1−/− mice in response to CR infection, we further bred DCLK1fl/fl;CDX2-Cre/ERT2 mice with Rag1−/− to generate double knockout (DKO) mice to see whether the DKOs are more susceptible to infectious colitis." (PMID 34226497, 2021). "To this end, we did, however, see moderate increase in DCLK1+ cells in Rag-1−/− mice treated with antibiotics suggesting that restoring crypt DCLK1 may help attenuate infectious colitis." (PMID 34226497, 2021).
Infertility (1 paper, 2016). "Unfortunately we were unable to generate Eμ-Myc;Rag-1-Cre;Mcl-1fl/fl mice due to issues with infertility." (PMID 26962682, 2016).
Listeria infection (1 paper, 2015). "T and B cell-deficient RAG1 HOIL-1 double KO mice succumbed to infection significantly faster than RAG1 KO mice, and exhibited elevated bacterial burden in the spleen and liver 3 days post-infection, indicating that HOIL-1 plays an essential role in innate immunity during Listeria infection." (PMID 25599590, 2015).
lymphoid leukemia (1 paper, 2012). A malignant lymphocytic neoplasm of B-cell or T-cell lineage involving primarily the bone marrow and the peripheral blood. "However, Rag1−/− mice with concomitant deletion of the tumor suppressor locus Cdkn2a also develop lymphoid leukemias, implying that mechanisms of lymphoid leukemia development are not entirely dependent on mistargeted V(D)J recombination." (PMID 23487523, 2012). "Given the normal role of V(D)J recombination in lymphoid development, inappropriate targeting of RAG1 and RAG2 has long been suspected in lymphoid leukemia initiation." (PMID 23487523, 2012).
lysosomal storage disease (1 paper, 2023). A metabolic disorder caused by mutations in proteins critical for lysosomal function, including lysosomal enzymes, lysosomal integral membrane proteins, and proteins involved in the post-translational modification and trafficking of lysosomal proteins. "This is supported by our previous treatment approaches in Rag1-deficient models of rare lysosomal storage diseases accompanied by T cell-driven axon degeneration, which also did not reveal major effects independent of immune cells." (PMID 37182098, 2023).
macrocytic anemia (1 paper, 2012). Anemia that is characterized by increased red blood cell volume. "Taken together, these findings indicate that the Rag1 status does not affect the macrocytic anemia which develops in the NHD13 mice." (PMID 22606303, 2012).
malaria (1 paper, 2010). Malaria is a serious and sometimes fatal disease caused by a parasite that commonly infects a certain type of mosquito which feeds on humans. "Similar levels of immunogenic MPs were produced in WT and in TNF−/−, IFN-γ−/−, IL-12−/− and RAG-1−/− malaria-infected mice, but were not produced in mice injected with LPS, showing that inflammation is not required for the production of MPs during malaria infection." (PMID 20126448, 2010).
medulloblastoma (1 paper, 2022). A malignant, invasive embryonal neoplasm arising from the cerebellum. "We found medulloblastomas in wildtype and Rag1-deficient mice grew equally fast, and that craniospinal irradiation and chemotherapies extended survival equally in wildtype and Rag1-deficient mice, suggesting that tumor growth and treatment response is independent of T and B cells." (PMID 35309309, 2022).
muscle-eye-brain disease (1 paper, 2021). "P14 had a homozygous RAG1 pathogenic variant as well as POMT1-associated muscle-eye-brain disease." (PMID 34539671, 2021).
mycobacterial infection (1 paper, 2014). "However, the expression levels of ifnγ were similar in rag1 (−/−) and WT fish showing that the induction of this Th1-type cytokine in mycobacterial infection might not be as dependent on functional lymphocytes as the other markers used." (PMID 24968056, 2014).
myeloid tumors (1 paper, 2013). "All four lymphoid cell lines (Reh, NALM-6, Jurkat, and SUP-T1) but not the myeloid tumors presented a RFP+GFP+ population when infected with GFPi, confirming the ability of the GFPi retrovirus to detect endogenous RAG1/2 activity." (PMID 23720659, 2013).
myocarditis (1 paper, 2019). Myocarditis is a condition that is characterized by inflammation of the heart muscle (myocardium). "Fortunately, only 1 patient from our cohort who was diagnosed with RAG1 deficiency developed OPV related complication (i.e., myocarditis)." (PMID 31191561, 2019).
neutropenia (1 paper, 2023). A decrease in the number of neutrophils found in the blood. "The absence of an effect on IL1β expression in the present study following neutropenia, RAG1 deficiency, or AT1 inhibition may be attributed to low levels of cytokine mRNA at 3 days post CCI15." (PMID 37150755, 2023).
oropharyngeal carcinoma (1 paper, 2016). Carcinoma, predominantly squamous cell, arising from the epithelial cells of the oropharynx. "Using in vivo mouse models, we revealed that restoration of Cxcl14 expression in HPV-positive mouse oropharyngeal carcinoma cells clears tumors in immunocompetent syngeneic mice, but not in Rag1-deficient mice." (PMID 27143385, 2016).
pancreatitis (1 paper, 2009). Inflammation of the pancreas. "Sf, Sf.Faslpr/lpr, Sf.Il2-/- or adult Rag1-/- mice that were intravenously transferred with Sf lymph node cells developed very mild pancreatitis with peri-vascular infiltration of leukocytes and occasional destruction of acini outside the islets." (PMID 19272184, 2009). "Interestingly, moderate to severe pancreatitis with strong leukocyte infiltration and severe destruction of acini was observed when Sf lymph node cells were transferred intraperitoneally into neonatal or adult Rag1-/- recipients." (PMID 19272184, 2009).
papilloma (1 paper, 2015). A benign epithelial neoplasm that projects above the surrounding epithelial surface and consists of villous or arborescent outgrowths of fibrovascular stroma. "Then, RAG1-KO C57BL/6 mice (n = 10) were first challenged with MusPV1 using a dose sufficient to produce small papillomas within 3–5 weeks." (PMID 26495972, 2015). "Adoptive transfer of a MusPV1 E6-specific CD8+ T cell line controlled established MusPV1 infection and papilloma in RAG1-knockout mice." (PMID 26495972, 2015).
pneumonia (1 paper, 2021). An acute, acute and chronic, or chronic inflammation focally or diffusely affecting the lung parenchyma, caused by an infection in one or both of the lungs (by bacteria, viruses, fungi, or mycoplasma.). "Here, we demonstrated that a single intranasal immunization of inactivated whole cell of Acinetobacter baumannii elicits rapid protection against broad A. baumannii-infected pneumonia via training of innate immune response in Rag1-/- mice." (PMID 34544549, 2021).
Progressive encephalopathy (1 paper, 2022). "In humans, progressive encephalopathy has been associated with RAG-1 deficiency, while RAG-1-deficient mutant mice show defects in memory formation and alterations in the olfactory system." (PMID 35742893, 2022).
proliferative glomerulonephritis (1 paper, 2015). A constellation of renal disorders characterized by an increase number of cells in the glomerulus; these disorders generally present with nephrotic syndrome, and generally progress to end stage renal failure over a matter of weeks to years, depending on the etiology. "Direct evidence that Th1 and Th17 cells may induce proliferative glomerulonephritis has been reported, where ovalbumin is planted in glomeruli of Rag1-/- mice which are deficient in T and B cells." (PMID 25964886, 2015).
prostate tumor (1 paper, 2020). "To directly assess the impact of lack of adaptive immunity on our previously observed GDF15 mediated reduction in PCa growth, we compared prostate tumor growth in a cohort of TRAMP (n = 22), TRAMPfmsmic-1 (n = 15), TRAMPrag-/- (n = 18) and TRAMPfmsmic/rag1-/- (n = 14) mice." (PMID 32502202, 2020).
psoriasis (1 paper, 2019). An autoimmune condition characterized by red, well-delineated plaques with silvery scales that are usually on the extensor surfaces and scalp. "In order to directly test the T cell–specific function of TIPE2 in psoriasis, we studied the IMQ-induced psoriasis in Rag1−/− mice that had received WT or TIPE2-deficient T cells." (PMID 31616442, 2019).
Renal adenocarcinoma (1 paper, 2009). "We performed siRNA mediated down regulation of nucleolin and NRP (smart pool, Dharmacon) in mouse GC1-Spg and RAG-1 (Renal adenocarcinoma) cell lines." (PMID 19570216, 2009).
Respiratory tract infection (1 paper, 2025). An infection of the upper or lower respiratory tract. "P4 was 18 months old when he was diagnosed with recombination activating gene 1 (RAG1) deficiency SCID following recurrent severe respiratory tract infections." (PMID 40237937, 2025).
Salmonella Infections (1 paper, 2019). Infections with bacteria of the genus SALMONELLA. "Analogously to Rag-1−/− mice, both non-immunized Igh−/− mice and Igh−/− mice vaccinated with either S.Tm transformants were equally susceptible to Salmonella infection, supporting a crucial role for SIgA in controlling the local infection and systemic spreading of the pathogen." (PMID 30651557, 2019).
squamous cell carcinoma (1 paper, 2016). A carcinoma arising from squamous epithelial cells. "Although IgG responses specific for the tumour are generated after ingenol mebutate treatment of B16 tumours (and T7 squamous cell carcinomas), the Rag1-/- experiments would suggest such responses have minimal impact on relapse rates of the ingenol mebutate treated tumours." (PMID 27100888, 2016).
T cell lymphomas (1 paper, 2019). "In addition, 9qA4-5.3 alterations were occasionally observed in T cell lymphomas arising after transfer of RAG1-deficient thymic cells into a progenitor-deprived “competition-free” recipient thymic environment." (PMID 31167132, 2019).
tenosynovitis (1 paper, 2015). Inflammation of the synovial lining of a tendon sheath. "Although others have found colocalized viral mRNA and tissue damage in younger RAG1-/- mice and have observed tenosynovitis for extended periods of time, we did not observe these findings using adult RAG1-/- mice." (PMID 26115459, 2015).
thymic carcinoma (1 paper, 2025). Thymic carcinoma (TC) is a type of thymic epithelial neoplasm characterized by a high malignant potential. "For under‐researched cancers like thymic carcinoma, the model prioritized DHCR24 and RAG1." (PMID 40784724, 2025).
tumor (212 papers, 2005 to 2026). "Next, the anti-tumor immune response of CBD was evaluated in immunocompetent syngeneic mouse as well as in immune-deficient B6.129S7-Rag1tm1Mom/J or Rag 1 Knockout mice (Rag1 -/-) and athymic nude mouse." (PMID 40475776, 2025). "To examine the tumoricidal function of CD8+ T cells, we transferred freshly isolated CD8+ T cells from WT or CD40L-deficient (CD40L−/−) mice into RAG1−/− mice, challenged these mice with TAg+ cancer cells, and measured tumor growth." (PMID 40397730, 2025). "After Hepa1-6 cell injection, Rag1−/− mice reconstituted with Id2fl/flCd4-Cre+ CD8+ T cells along with Id2fl/flCd4-Cre− CD4+ T cells displayed increased tumor susceptibility, as shown by the elevated tumor burden." (PMID 38287103, 2024). "We next transplanted Cyp11b1‐proficient and Cyp11b1‐deficient tumoroids into lymphopenic Rag1‐deficient mice to monitor the contribution of T and B cells in the control of tumour growth." (PMID 36861295, 2023). "EA2 cells were also inoculated into the orthotopic site of immune-deficient Rag1−/− mice and the resulting tumor-bearing mice were treated with diluent or alectinib." (PMID 36739466, 2023). "As compared with wild-type CD8+ T cells, Ramp1−/− CD8+ T cells were protected against exhaustion when co-transplanted into tumour-bearing Rag1-deficient mice." (PMID 36323780, 2022). "After MC38 tumor challenge, Rag1-KO mice reconstituted with PTEN-deficient CD8+ T cells plus WT CD4+ T cells had enhanced antitumor immunity." (PMID 35143421, 2022). "With this aim, SMYD2-proficient and -deficient HT-29 cells were implanted into Rag1−/− mice via subcutaneous injection, and tumor development was monitored over time." (PMID 35022391, 2022). "To define the role of pIgR-mediated IgA transcytosis in anti-tumour activity, we challenged RAG1-deficient mice with PIGR-ablated OVCAR3 tumours." (PMID 33536615, 2021). "Accordingly, treatment with non-antigen-specific IgA significantly delayed the growth of OVCAR3 tumours in RAG1-deficient tumour-bearing mice, compared to control IgG or pepsinized IgA." (PMID 33536615, 2021). "Tumor regression was T-cell mediated, as was seen with the loss of cDLL1 efficacy in tumor-bearing Rag1–/– mice and mice receiving anti-CD8 antibody to deplete CD8+ T cells." (PMID 32922403, 2020). "The importance of NK cells in this setting is supported by the finding that IL-15C improves tumor clearance in Rag1-deficient mice, which lack CD8+ T cells." (PMID 31552035, 2019). "As in Il2rg-/- mice that are genetically deficient for NK cell production, tumor cells engrafted more efficiently in Rag1-/- mice that had been depleted of NK cells with NK1.1 antibody compared to control antibody treated Rag-/- mice." (PMID 30936429, 2019). "DMXAA treatment of KPC1242 tumors engrafted to RAG-1-deficient recipients had a similar impact on tumor growth as that observed in CD8-depleted wild-type mice." (PMID 31036082, 2019). "A combined loss of lymphocytes by knockout of recombination activating gene-1 or − 2 (rag-1 or − 2), or by other methods, has demonstrated an even greater incidence of spontaneous and carcinogen-induced tumor formation in mice." (PMID 29751789, 2018). "In line with this, the anti-tumor effects of recombinant IL-9 administration were conserved in tumor-bearing Rag1-deficient mice, suggesting that other immune effectors are involved in the anti-cancer effects observed." (PMID 27832300, 2017). "For this, they injected TH9 cells into tumor-bearing Rag1-deficient mice, which lack T and B cells, and found that the anti-tumor potential of TH9 cells was conserved in the absence of adaptive immunity." (PMID 27832300, 2017).